CD4 (CD4 molecule)
Diseases named in the same sentence as CD4 in open-access papers (continued):
Sharing a sentence is not in itself a finding about the gene and the disease.
tumor (continued). "Thus effective tumor immunity is often dependent on such complex CD4 T cell responses following polarization and their interactions with other Th cell subsets within the hostile tumor environment." (PMID 23533029, 2013). "There is ample evidence supporting the hypothesis that tumors convert CD4+FoxP3− (Tconv) into CD4+FoxP3+ (iTreg) by tumor-derived signals, while others suggest that nTregs are recruited and/or expanded by the tumor." (PMID 23720663, 2013). "In addition to enhancing and/or regulating T cell-mediated responses, that include both promoting long-term immunity and establishing or rebalancing immune cell homeostasis, CD4 T cells can also have a direct role in tumor elimination." (PMID 23533029, 2013). "In addition, tumor-infiltrating Tim-3+Foxp3+ CD4 T cells expressed higher levels of CTLA-4, GITR and PD-1 compared with Tim-3−Foxp3+ CD4 T cells." (PMID 23526963, 2013). "Consequently, the anti-tumor efficacy of the MUC1 vaccine was mediated by CD4+ T cells, FasL, and TNF-α signaling, resulting in induction of the innate immunity and apoptosis." (PMID 23675573, 2013). "In contrast, CD4+CD25highFoxP3+ regulatory T cells (Treg cells) can stimulate tumor growth." (PMID 24312450, 2013). "Tregs secrete transforming growth factor-beta (TGF-β) and interleukin-10 (IL-10), which down-regulate antitumour immunity, suppressing the antigen presentation by DCs, CD4+ T helper (Th) cell function and the generation of tumour specific CD8+ cytotoxic T lymphocytes (CTLs)." (PMID 23320561, 2013). "Moreover, if these highly proliferative CD4+Foxp3+helios+ cells are, as this study suggests, suppressive within the tumor microenvironment then the available evidence favors intra-tumoral expansion of tTreg as a major mechanism of Treg enrichment in tumors." (PMID 23874342, 2013). "Therefore, we examined the distribution of Tim-3+ CD4 cells throughout the tumor tissues using multi-color immunofluorescence, paying particular attention to their micro-anatomic location." (PMID 23526963, 2013). "In contrast, EW-7197 showed significant anti-tumour efficacy on deletion of CD4+ cells or NK cells." (PMID 24127404, 2013). "Accordingly, a recent analysis of Treg subsets in Her2/Neu-expressing mammary tumor-bearing mice revealed the existence of a Cy-sensitive CD4+Foxp3+CD25+ subset with tumor-seeking migratory phenotype, characteristic of amTregs, and capable of high avidity T-cell suppression." (PMID 24133490, 2013). "90K protein has been reported to be expressed in many tissues and tumor cell lines, but whether it is expressed in CD4+ T-cells and macrophages that represent the primary HIV-1 target cells in vivo is poorly investigated." (PMID 24156545, 2013). "To analyze whether CD4, CD25, Foxp3, IL-10, and TGF-β expression in CRC may be associated with clinical tumor progression we investigated tumors of limited disease (UICC I/II) and advanced disease (UICC III/IV)." (PMID 23382847, 2013). "In addition, the presence of ARG2-expressing stromal cells was closely correlated with higher tumor-infiltrating CD68+ macrophages and CD66b+ neutrophils, and lower tumor-infiltrating CD4+ T cells and CD8+ T cells." (PMID 23424623, 2013). "Importantly, patients receiving antiOX40 treatment had an increase in tumor-specific immune responses after therapy and had increased CD4+ and CD8+ T-cell proliferation." (PMID 23840967, 2013). "Whether Th17 lymphocytes are induced de novo from naïve CD4+ T cells or recruited at the tumor site or originate from “reprogrammed Treg” (see previous section and below) remains to be elucidated." (PMID 24454480, 2013). "Also immune responses against autologous tumor cells in imatinib-treated CML patients were dominated by CD4+ T cells." (PMID 24348684, 2013). "Conceivably, this trait of “cellular Darwinism” by the various CD4 T cell lineages could endow them with considerable flexibility to procure effective tumor immunity." (PMID 23533029, 2013).
tumor (continued). "Similarly, CD4+ tumor infiltrating lymphocytes (TIL) as a percentage of total lymphocytes were decreased compared to CD4+ T cells in normal liver (8.7% ± 1.9 vs. 18.8% ± 2.5, p = 0.00002)." (PMID 23514280, 2013). "Importantly, the combined therapy reduces regulatory T cells (Treg) in the tumor-draining lymph nodes and induces a long-lasting T-cell–mediated immune response against tumors involving both CD4+ and CD8+ T cells." (PMID 24156020, 2013). "Given that CD8+ T cells play a critical role for the elimination of tumor in both models, we speculate that the effect of CD4+ T cell depletion on therapeutic efficacy of vaccines goes through CD8+ T cells as a downstream target." (PMID 24066030, 2013). "Unlike CD25 and CD127, which characterize Treg in both peripheral blood and tumor tissues, Tim-3 is not expressed by circulating Foxp3+ CD4 T cells, indicating that Tim-3 is specifically expressed on tumor associated Tregs." (PMID 23526963, 2013). "The stromal (i.e., non-follicular) immune cell content increased overall with tumor stage and was characterized by a higher number of CD8+ T cells than CD4+ T cells at each stage (CD8 vs. CD4 cells for normal ovary, p = 0.003; early stage tumor, p = 0.008 and late stage tumor, p = 0.007)." (PMID 24040191, 2013). "There is now a wealth of evidence indicating that factors present in the tumor microenvironment can foster immune tolerance by generating and inducing the functional capacity of CD4+CD25high Treg cell populations and the induction of antigen-specific regulatory T cells from naïve cells." (PMID 23378947, 2013). "Thus, in 5 out of 9 patients intraperitoneal administration of trifunctional antibodies such as catumaxomab induced a significant increase of tumor reactive CD4+/CD8+ T-lymphocytes with a prolonged survival." (PMID 24380380, 2013). "Increasing the CD4+/CD8+ T-cell ratio may improve the antitumor ability and is associated with a reduced risk of tumor recurrence." (PMID 24649272, 2013). "However, tumor exposure to ultra low-dose RFA induced a significant increase in CD4+ T-cell response relative to controls." (PMID 23894654, 2013). "The results of the present study reveal that different tissue contexts may determine the phenotype and function of Tim-3+ CD4 T cells in the tumor microenvironment." (PMID 23526963, 2013). "After exposure to LF-MF, CD3 + CD4+ T cells significantly increased in tumor-bearing mice." (PMID 24314291, 2013). "However, CD4+ T cells have been recently reported to act directly against tumor cells by elimination of the targets." (PMID 24205259, 2013). "However, tumor burden and radiation therapy is accompanied by an increase in the number of T regulatory cells (Treg) in the spleen, as measured by CD4+ cells expressing CD25 and FoxP3." (PMID 23936036, 2013). "Accumulating evidence indicates a pivot role of Akt/mTOR pathway in regulating CD4 + Foxp3+ regulatory T cells in tumor microenvironment.Therefore, targeting mTOR by rapamycin may be a promising therapeutic strategy for ASCC." (PMID 24124460, 2013). "Although the clinical application and therapeutic effects of directly administered recombinant IFN-γ in cancer patients appears marginal, there is limited experience in investigations focused on therapies utilizing direct transfer of tumor-reactive CD4 T cells secreting IFN-γ." (PMID 23533029, 2013). "Furthermore, these tumor-infiltrating CD4+Foxp3− T cells were able to suppress T-cell proliferation in vitro in an IL-35-dependent fashion, indicating that tumor establishment led to the generation of iTr35 cells." (PMID 24151492, 2013). "The sources of circulating Th17 cells may include the differentiation of Th17 cells from CD4+ T cells and the entry of tumor-infiltrating Th17 cells into the circulation." (PMID 23565248, 2013). "Therefore, CD8 or CD4 Th1 cells favor anti-tumor activities, while Th2, Th17, and Treg populations favor pro-tumor and/or immunosuppressive conditions." (PMID 23577028, 2013).
tumor (continued). "On the other hand, PD-1+Tim-3− cells may represent the bona fide population of exhausted CD4 T cells in tumor tissue." (PMID 23526963, 2013). "An interesting molecule that may control CD40L+CD4+ T cell adhesion to endothelium is CD40 which can be expressed at higher levels by tumor endothelial cells relative to endothelia in normal tissues." (PMID 24013775, 2013). "Importantly, combined OK-432- and PSK-activated DC/tumor vigorously induced IFN-γ-producing CD4+ and CD8+ T cells." (PMID 23555011, 2013). "A recent study analyzed T antigen-induced multistage carcinogenesis in pancreatic islets and found that while in wild type mice infiltrating CD4+ T cells induced tumor dormancy, loss of TNFR1 on these cells switched them to a tumor-promoting phenotype by stimulating angiogenesis." (PMID 24098720, 2013). "All tumor samples showed CD4+CD25+FOXP3+ Treg infiltration with a combined range of 14-350 cells." (PMID 24244610, 2013). "Taken together, our results show that combined OK-432- and PSK-activation of DC/tumor contributes to enhance their ability through a fusion process to stimulate IFN-γ-producing CD4+ and CD8+ T cells and may enable stronger CTL responses to be generated." (PMID 23555011, 2013). "A previous study showed that the local tumor immune microenvironment plays an important role in cancer suppression and promotion and that one of the main factors leading to tumor immune tolerance in the local tumor microenvironment is the influence of CD4+/CD25+/FOXP3+ regulatory T cells (Tregs)." (PMID 23759077, 2013). "In addition, we provide evidence that inactivation of Tregs enhances the potency of vaccination with DC/tumor cell fusions in a synergistic fashion, and that the enhancement of anti-tumor activity was primarily mediated by CD4+ T-effector cells." (PMID 23768240, 2013). "To determine whether tumor-derived Tim-3+ CD4 T cells are dysfunctional Th1 cells, we quantified expression of the Th1-specific transcription factor T-bet and the well-recognized exhausted/anergic marker PD-1 on Tim-3+ CD4 T cells." (PMID 23526963, 2013). "Both the tumor-infiltrating CD4+ cells and macrophages expressed abundant levels of galectin-9." (PMID 23526963, 2013). "However, OX40 is a very specialized marker expressed primarily by recently activated CD4+ T lymphocytes showing preferential accumulation at tumor sites in cancer patients and is thought to represent tumor antigen specific T cells." (PMID 23418928, 2013). "In those experiments, in which DNA vaccine was used for immunization, depletion of CD8+ T cells did not abolish the antitumor effect while depletion of CD4+ T cells rendered mice susceptible to tumor formation." (PMID 24348684, 2013). "We especially focused on the direct anti-tumor effect of CD4+ T cells and found that these cells could fully compensate for the lack of cytotoxic CD8+ T cells when their functional suppression by Tregs was interrupted." (PMID 22890822, 2013). "Activated CD4+ T cells may partner with many different types of host cells to clear the tumor indirectly by secretion of vast array of cytokines." (PMID 24348684, 2013). "The accumulation of Tim-3+Foxp3+ CD4 T cells in the cancer nest other than in peritumoral stroma implied that Tim-3+ Tregs could be induced during tumor progression." (PMID 23526963, 2013). "Thus, we propose elevated levels of the cFOXP3/nFOXP3 ratio within tumor infiltrating CD4+ T cells as a predictor of OSCC recurrence." (PMID 23977174, 2013). "In addition to these direct epigenetic effects on components of the antigenic response within cancer cells, the tumor microenvironment has also been shown to epigenetically drive tumor infiltrating CD4+ T cells to tolerance." (PMID 24062768, 2013). "Thus, we believe that tumor-specific CD4+ T cells can facilitate direct anti-tumor activity, which can be supported by TRAIL+ macrophages inducing the classical macrophage activation pathway that contributes to inhibition of tumor cell growth." (PMID 22890822, 2013).
tumor (continued). "Interestingly, Tg8 CD4-Cre PS1fl/+ PS2-/- mice showed a slight delay in tumor onset compared to Tg8 CD4-Cre PS1+/+ PS2-/- mice, probably due to lower Notch activation." (PMID 24386421, 2013). "Alternatively, another group using IL-10 knockout mice showed that IL-10 indirectly hindered tumor development, growth, and progression by impeding the development of both MDSCs and CD4+ TReg cells which presumably contributed to immune suppression, carcinogenesis, and tumor pathology." (PMID 23533029, 2013). "However, our in vivo experiments strongly suggest cytotoxic activity of CD4+ T cells against FBL-3 tumor cells." (PMID 22890822, 2013). "Finally, Tregs can secrete two of the main immuno-suppressive cytokines: IL-10 and TGF-β that blunt anti-tumor effector cells such as CD4+, CD8+, and NK." (PMID 24339825, 2013). "Inoculation of GM-CSF producing tumor cells also expanded total CD11c+ cell numbers but failed to restore the CD4+ DC compartment in EBI2-deficient mice (not shown)." (PMID 23682316, 2013). "Moreover, to identify the cells infiltrated into the tumor tissues, tumor sections were examined by immunohistochemistry using anti-CD4 or anti-CD8 monoclonal antibodies." (PMID 23844018, 2013). "For example, Th1 cells may possess homeostatic functions under select conditions within the tumor that can influence the generation, survival and balance of CD4 and CD8 effector and memory T cell subpopulation pools necessary for effective antitumor responses." (PMID 23533029, 2013). "To determine whether tumor-derived Tim-3+ CD4 T cells are functional Tregs, we first examined the expression of functional inhibitory markers of Tregs on these cells." (PMID 23526963, 2013). "The data clearly indicated that the TCR repertoires of tumor-infiltrating Foxp3− and Foxp3+CD4+ T cells are distinct, implying that at least in the case of carcinogen-induced tumors, conversion of conventional T cells is not a significant cause of intra-tumoral Treg enrichment." (PMID 23874342, 2013). "However, the role of CD4+ T cells in anti-tumor immune responses generated by various immunotherapeutic strategies, particularly active vaccination, remains to be fully elucidated." (PMID 24066030, 2013). "In addition, CD4+ T cells can support killing of tumor cells by indirect mechanisms including recruitment of antigen-presenting cells or killing stroma cells that support tumor growth." (PMID 22890822, 2013). "One may speculate that the background diet may have some degree of anti-tumor activity, but the fact is the populations of CD4+CD25+Fox-p3+ Tregs and CD11b+Gr-1+ MDSCs in TB mice are much higher than those in TB-Con mice." (PMID 23349693, 2013). "To provide direct evidence and assess the relative roles of these cells, we herein used antibodies to CD4 and CD8 molecules to deplete CD4+ or CD8+ T cells one day before vaccination with the optimized therapeutic SA-4-1BBL/E7 formulation using the TC-1 tumor model." (PMID 24066030, 2013). "Thus, both CD8+ and CD4+ T-cell populations in drLN expressed pro-inflammatory cytokines and GzmB in response to tumor challenge, but the CD4+ T-cell response initiated earlier and the magnitude of the response was higher than the CD8+ T-cell response." (PMID 22890822, 2013). "However, the task of effector CD4+ T cells and Tregs should also be analyzed in effective anti-tumor immunity to fully understand their role in tumor biology." (PMID 22890822, 2013). "Furthermore, tumor-related factors activate CD4+CD25high Treg cells, expand CD4+CD25high Treg cells and enhance their suppressive capacity." (PMID 23378947, 2013). "Therefore, it is likely that Th1 CD4+ T cells play a critical role in conditioning a tumor-inhibiting inflammatory milieu that facilitates immune activation and tumor destruction." (PMID 22400040, 2012).
tumor (continued). "Moreover, tumor cells caused by HTLV-1 express both PD-1 and PD-L1, and infiltrating T cells express PD-1, suggesting that PD-L1 expressed on these neoplastic CD4+ T cells induce immunosuppression of infiltrating T cells and contribute to the immune evasion." (PMID 22612856, 2012). "Early studies in rats and mice indicated that adoptive transfer of tumour-specific CD4+ T cells may be very efficient in eradicating established cancers." (PMID 22649466, 2012). "Additionally, we show that COX2 over-expression in TM40D tumors alters their immune profile from a high infiltration of antitumor CD4+ T helper cells, to a high tumor frequency of suppressive CD4+ FoxP3+ Tregs." (PMID 23029485, 2012). "Several immune evasion mechanisms were proposed to explain this: low expression of MHC I in MCC, defective homing or effector functions of CD8+ T cells or induction of regulatory-like CD4+ T cells which might promote tumor growth." (PMID 23029236, 2012). "The inhibition of tumour-generated CD4+ TReg cells through abolition of cell-to-cell contact was associated with a reduction in the production of IL-10 (69.8±33.6 pg/ml vs 6.3±0.01 pg/ml, n = 3, p = 0.079) and IFNγ (12154±4174 pg/ml vs 0.04±0.01 pg/ml, n = 3, p<0.001)." (PMID 22666318, 2012). "We herein tested this hypothesis by investigating the effect of immunomodulation with SA-4-1BBL on antigen-, TGF-β-, and tumor-mediated conversion of conventional CD4+ T cells into iTreg cells." (PMID 22870329, 2012). "Both CD8+ and CD4+ T cells infiltrated into local tumor tissues following DCLV-PSCA immunization." (PMID 23139820, 2012). "One important implication of CD4+ T-cell cytotoxicity is that CD4+ T-cell-mediated tumor destruction may result in antigen spreading, which is associated with broadened antitumor CD8 responses and improved clinical responses." (PMID 22400040, 2012). "Our study may provide a platform for in vitro generating antigen-specific cytotoxic CD4+ T cells for adoptive tumor immunotherapy." (PMID 23145026, 2012). "Moreover, in many tumor entities, the recruitment of thymus-derived “natural” CD4+CD25+FoxP3+ regulatory T cells (nTregs) contributes to the immunosuppressive status." (PMID 22674057, 2012). "Vaccine efficacy was associated with robust tumor-reactive primary and memory CD8+ T effector responses, Th1 cytokine response, higher intratumoral CD8+ T effector/CD4+CD25+Foxp3+ T regulatory cell ratio, and reduced myeloid derived suppressor cells in the spleen." (PMID 22860107, 2012). "Other mechanisms of action may include increased Treg migration from the circulation or Treg differentiation in the tumor from CD4+ T cells." (PMID 23029485, 2012). "Importantly, activated CD4 T cells are a major source of IFNγ, an effector cytokine with potent tumor regressing activity via inhibition of tumor-induced angiogenesis or activation of tumor-infiltrating macrophages." (PMID 22400038, 2012). "Moreover, tumor Ag-specific CD4+CD25+FoxP3+ Treg were evidenced in the blood of patients with metastatic CM." (PMID 22924051, 2012). "As for the CD4+ T cells, several possible reasons explain their requirement for tumor protection." (PMID 23139820, 2012). "However, we initially reported that a vaccinia virus-based therapeutic vaccine indiscriminately expanded both CD4+ effector T cells and Tregs in tumor-bearing hosts, resulting compromised antitumor immune responses." (PMID 22778760, 2012). "Indeed, the frequency of CD4+CD25+FoxP3+ regulatory T cells was increased in lymph nodes of tumor-bearing LLA-TG-3 mice compared to tumor-free LLA-TG-3 mice." (PMID 22674057, 2012). "The possible effect of cyclophosphamide to enhance the antitumor efficacy of DC vaccine may be due to the increasing proportion of IFN-γ secreting lymphocytes in combination with the suppressing proportion of CD4+CD25+FoxP3+ Treg cells in tumor-bearing mice." (PMID 22481968, 2012).